NORAD (non-coding RNA activated by DNA damage)
Diseases named in the same sentence as NORAD in open-access papers (continued):
Sharing a sentence is not in itself a finding about the gene and the disease.
endometrial cancer (4 papers, 2020 to 2021). Primary or metastatic malignant neoplasm involving the endometrium (mucous membrane that lines the endometrial cavity). "Based on the assessment of data available in The Cancer Genome Atlas (TCGA) as well as an independent cohort of patients with endometrial cancer, expression of NORAD has been decreased in endometrial cancer samples compared with normal tissue samples in association with cancer progression." (PMID 34485302, 2021). "Expression of NORAD has been down-regulated in endometrial cancer cells." (PMID 34485302, 2021). "In an opposite fashion, NORAD works as a tumor suppressor by binding FUBP1 and promoting cell apoptosis in endometrial cancer." (PMID 33739352, 2021).
esophageal cancer (4 papers, 2020 to 2024). A primary or metastatic malignant neoplasm involving the esophagus. "In this study, the lnc-RNA NORAD was upregulated in esophageal cancer cells in response to DNA damage following exposure to radiation." (PMID 37835506, 2023). "Expression of the WRAD subunits ASH2L and RbBP5 was positively correlated with NORAD expression in esophageal carcinoma tissues." (PMID 34587992, 2021).
diabetic nephropathy (3 papers, 2020 to 2021). "In addition, lncRNA NORAD upregulates TLR4 expression via targeting miR-520h to promote the progression of diabetic nephropathy." (PMID 34307380, 2021). "Moreover, upregulation of NORAD was demonstrated to affect the progression of diabetic nephropathy through targeting miR-520 h to increase the expression of TLR4." (PMID 33292272, 2020).
ovarian carcinoma (3 papers, 2020 to 2024). A malignant neoplasm originating from the surface ovarian epithelium. "A similar axis also exists in ovarian cancer, but surprisingly, NORAD induces overexpression of signal transducer and activator of transcription 3 (STAT3) by interacting with miR-608 and functions as a tumor suppressor." (PMID 35387124, 2022). "For example, NORAD silencing reduces ovarian cancer cell activity, migration, and invasion but induces cell apoptosis through the NORAD/miR-608/STAT3 axis." (PMID 32267831, 2020).
thyroid cancer (3 papers, 2021 to 2022). "Increased NORAD expression can inhibit the expression of miR-202-5p, thereby driving the proliferation and malignancy of thyroid carcinoma cells." (PMID 36217480, 2022).
liver cancer (2 papers, 2022 to 2023). An epithelial or non-epithelial malignant neoplasm that arises from the liver. "Despite this association, it was also described previously in liver cancer that NORAD functions as a potential tumor suppressor." (PMID 37680988, 2023).
lymph node metastasis (2 papers, 2021 to 2022). "However, another study by Tan and his colleagues revealed the downregulation of NORAD in LC and its association with lymph node metastasis and poor prognosis." (PMID 36245705, 2022). "Besides, NORAD is activated in non-small cell lung cancer (NSCLC) and predicts poor overall survival and lymph node metastasis in an advanced stage of NSCLC." (PMID 36245705, 2022). "We found that NORAD expression was significantly correlated with CDDP sensitivity, TNM stage, invasion range and lymph node metastasis but not correlated with sex or age." (PMID 34893064, 2021).
Parkinson disease (2 papers, 2021 to 2025). A progressive degenerative disorder of the central nervous system characterized by loss of dopamine producing neurons in the substantia nigra and the presence of Lewy bodies in the substantia nigra and locus coeruleus. "For instance, NORAD is down-regulated in the MPP +-mediated Parkinson’s disease model, and overexpressing NORAD weakens the MPP+-induced cytotoxicity in SH-SY5Y cells." (PMID 34895039, 2021).
psoriasis (2 papers, 2023 to 2025). An autoimmune condition characterized by red, well-delineated plaques with silvery scales that are usually on the extensor surfaces and scalp. "In psoriasis and head and neck squamous cell carcinoma, NORAD negatively manages miR-26a." (PMID 36726840, 2023). "Notable representation is also observed in psoriasis and autoimmune diseases, particularly through lncRNAs such as TINCR, MALAT1, and NORAD, as well as miRNAs like miR-17-5p, miR-26b-5p, and let-7i-5p." (PMID 40725409, 2025).
Sepsis (2 papers, 2022 to 2026). Sepsis is defined as life-threatening organ dysfunction caused by a dysregulated host response to infection. "Acute lung injury (ALI) is a severe complication of sepsis, yet the role of lncRNA NORAD in its pathogenesis remains unclear." (PMID 41776820, 2026).
triple-negative breast carcinoma (2 papers, 2023 to 2024). An invasive breast carcinoma which is negative for expression of estrogen receptor (ER), progesterone receptor (PR), and human epidermal growth factor receptor 2 (HER2). "Here, we demonstrate that NORAD downregulation sensitizes triple-negative breast cancer cells to chemotherapy, through a potential accumulation of genomic aberrations and an impaired capacity to signal DNA damage." (PMID 37680988, 2023). "Consequently, reducing NORAD levels was found to sensitize triple-negative breast cancer cells to chemotherapy, potentially due to an increased accumulation of genomic abnormalities and a reduced ability to detect DNA damage." (PMID 39479021, 2024).
acute myocardial infarction (1 paper, 2023). Necrosis of the myocardium, as a result of interruption of the blood supply to the area. "In acute myocardial infarction, NORAD knockdown inhibits infarct size and fibrosis in a rat model." (PMID 36726840, 2023).
breast adenosis (1 paper, 2023). A non-neoplastic disorder characterized by epithelial and/or myoepithelial tissue growth in the breast lobules. "The expression level of NORAD in the serum of BRCA patients (1.71, 0.33, 8.81) was significantly higher than that of healthy individuals (0.70, 0.62, 1.67), breast fibroma patients (1.54, 0.39, 2.68), and breast adenosis patients (1.00, 0.33, 2.14)." (PMID 37993524, 2023).
breast fibroadenoma (1 paper, 2023). "Our survival analysis revealed a strong relationship between NORAD expression and DSS as well as DFI, and ROC curve studies showed significant potential in the diagnosis of breast fibroadenoma and BRCA." (PMID 37993524, 2023).
Cerebral ischemia (1 paper, 2021). Restriction of arterial blood supply to the brain associated with insufficient oxygenation to support the metabolic requirements of the tissue. "To further elucidate the biological role of lncRNA NORAD in the cerebral ischemia/reperfusion injury, we measured the cell viability and lncRNA NORAD level in OGD/R-injured SH-SY5Y cells." (PMID 34709972, 2021). "In general, lncRNA NORAD may play a vital role in cerebral ischemia/reperfusion injury by sponging miR-30a-5p to increase YWHAG expression." (PMID 34709972, 2021).
colorectal adenocarcinoma (1 paper, 2018). The most common type of colorectal carcinoma. "lncRNA NORAD, amplified in 8% of colorectal adenocarcinoma, regulated genomic stability by sequestering PUMILIO protein." (PMID 30216655, 2018).
COVID-19 (1 paper, 2025). A disease caused by infection with severe acute respiratory syndrome coronavirus 2. "The observed upregulation of GAS5, NORAD, BISPR, and NEAT1 in dRNA-seq of infected Calu-3 cells (1.03- and 1.11-fold) is consistent with upregulation of these lncRNAs in COVID-19 patients (1.05- and 1.17-fold) in the two datasets (GSE171110 and GSE157103)." (PMID 41267684, 2025). "The upregulation observed of GAS5, NORAD, BISPR, and NEAT1 in dRNA-seq of infected Calu-3 cells (between 1.03- and 1.11-fold) is consistent with upregulation of these lncRNAs in COVID-19 patients (1.05- and 1.17-fold) in the two datasets (GSE171110 and GSE157103)." (PMID 41267684, 2025).
disc degeneration (1 paper, 2022). "NORAD was downregulated during disc degeneration and NPC senescence, while overexpression of NORAD inhibited NPC senescence in vitro." (PMID 35304463, 2022).
endometrioid endometrial adenocarcinoma (1 paper, 2020). "The results illustrated that low NORAD expression predicted a poor prognosis in endometrioid endometrial adenocarcinoma (the major subtype of EC)." (PMID 32555178, 2020).
fracture (1 paper, 2023). "The expression of NORAD in patients with hand fracture and the intra-articular fracture was both decreased compared with control individuals (P < 0.001)." (PMID 36726840, 2023).
hand fracture (1 paper, 2023). "The expression level of serum NORAD in patients with hand fracture and the intra-articular fracture was detected by qRT-PCR." (PMID 36726840, 2023).
Hepatic fibrosis (1 paper, 2022). The presence of excessive fibrous connective tissue in the liver. "The functional experiment further illustrated the role of the NORAD/miR-495-3p axis in hepatic fibrosis." (PMID 35200103, 2022). "Collectively, our data indicate that NORAD exhibits anti-fibrogenic activity in hepatic fibrosis." (PMID 35200103, 2022). "Therefore, in this study, we hypothesized that NORAD might play an important role in hepatic fibrosis by regulating the miR-495-3p/S1PR3 axis." (PMID 35200103, 2022). "However, the role and mechanisms of the lncRNA NORAD in hepatic fibrosis remain unclear." (PMID 35200103, 2022). "Therefore, this study was aimed at investigating the role of the NORAD/miR-495-3p-S1PR3 axis in the activation of HSCs, and revealing its mechanism, thereby providing a new theoretical basis for the treatment of hepatic fibrosis." (PMID 35200103, 2022). "NORAD inhibition could suppress HSC activation by modulating the miR-495-3p/S1PR3 axis, providing new insights for hepatic fibrosis treatment." (PMID 35200103, 2022).
hyperlipidemia (1 paper, 2024). "NORAD has been shown to be up-regulated by aging, hypoxia, lipopolysaccharide, and hyperlipidemia in endothelial cells all of which are well-known factors that can increase vascular permeabilities." (PMID 38898501, 2024).
Hypertension (1 paper, 2023). The presence of chronic increased pressure in the systemic arterial system. "Nevertheless, the underlying molecular mechanisms by which NORAD is overexpressed and causes hypertension are still unknown." (PMID 37894897, 2023). "For instance, the expression level of lncRNA NORAD is related directly to hypertension in preeclampsia." (PMID 37894897, 2023).
Kawasaki disease (1 paper, 2023). A rare inflammatory disease characterized by an acute febrile, systemic, self-limiting, medium-vessel vasculitis primarily affecting children. "In this study, the TOP4 lncRNAs common to most miRNAs were exhibited, the studies have found that The NEAT1/NORAD/XIST has-miR-204 axis regulates the development of Kawasaki disease (KD)." (PMID 37483435, 2023).
lung adenocarcinoma (1 paper, 2022). A carcinoma that arises from the lung and is characterized by the presence of malignant glandular epithelial cells. "According to the study developed by Kawasaki, NORAD overexpression catalyzed the risky epithelial-to-mesenchymal transition of cancer cells, to stimulate lung adenocarcinoma development." (PMID 36245705, 2022).
lymphopenia (1 paper, 2022). Reduction in the number of lymphocytes. "As a lncRNA activated by DNA damage, NORAD expression might increase due to aberrant SARS-CoV-2 replication, and its upregulation has been shown to reduce the growth of a lymphoblastoid cell line, suggesting a potential role of NORAD in lymphopenia." (PMID 36052163, 2022).
metastatic tumors (1 paper, 2022). "HE staining showed that compared with NC-agomir group, miR-378c-agomir alleviated the metastasis and infiltrative growth of metastatic tumors, which was rescued by injecting NRP1 or NORAD-overexpressed cells." (PMID 35164743, 2022).
multiple sclerosis (1 paper, 2024). A progressive autoimmune disorder affecting the central nervous system resulting in demyelination. "Enhanced NORAD activity has been reported under various conditions resulting in severe cell stress, for example, in damaged neurons in inflamed multiple sclerosis lesions." (PMID 38834884, 2024).
cancer (58 papers, 2016 to 2025). A tumor composed of atypical neoplastic, often pleomorphic cells that invade other tissues. "NORAD, recognized as an oncogene, has been linked to an unfavorable prognosis in different types of cancers." (PMID 37706018, 2023). "The lncRNA NORAD facilitates cancer development, whose expression is upregulated and associated with poor prognosis in several cancers, including bladder, squamous cell, breast, colorectal, esophageal, and pancreatic cancers." (PMID 37614816, 2023). "In the initial studies, NORAD was associated with genomic instability, and most subsequent research linked NORAD dysregulation to many cancers." (PMID 37517088, 2023). "NORAD contributes to cancer development, and its expression is upregulated and associated with poor prognosis in various types of cancers, including colorectal cancer, pancreatic cancer, breast cancer, esophageal squamous cell carcinoma and bladder cancer." (PMID 33435206, 2021). "NORAD has a crucial function in carcinogenesis, and its dysregulation has been implicated in various types of cancers." (PMID 34771549, 2021). "Upregulation of NORAD is associated with 6 different types of cancers, and overexpression of NORAD leads to poor overall survival in cancer patients." (PMID 33520952, 2020). "Though lncRNAs are known to be less conserved across species, conversely and of interest, we found NORAD to be highly conserved across multiple mammalian species, in addition to previous reports of its overexpression associated with multiple cancer phenotypes." (PMID 33520952, 2020). "Elevated NORAD expression in tumor tissues is linked to poor prognosis and recurrence, demonstrating the clinical significance of this molecule during cancer progression." (PMID 29121972, 2017). "Due to NORAD’s extensive network of binding partners, it has been associated with different pathological conditions including cardiovascular, cerebrovascular and degenerative diseases, but mostly with cancer." (PMID 38339387, 2024). "Interestingly, NORAD is dysregulated in different cancer types and is associated with tumorigenesis." (PMID 34895039, 2021). "To further investigate the molecular mechanisms underlying these events, we explored whether NORAD regulates EMT in cancer cells." (PMID 29121972, 2017). "Importantly, NORAD deficiency could sabotage cancer cell proliferation, expansion, and metastasis as well as encourage cell loss in LC." (PMID 36245705, 2022). "Among the highly expressed lncRNAs are GAS5 (also known as SNHG2), SNHG1, NORAD, and NEAT1, abundant transcripts implicated in cell-cycle control, cancer progression, DDR, and inflammation, respectively." (PMID 41369348, 2025). "Although NORAD’s involvement in maintaining genomic stability makes it a potential tumor suppressor, its impact on cancer remains intricate and contradictory." (PMID 38791575, 2024). "In other studies, NORAD is considered a tumor suppressor as its expression levels are lower in BC tissues and cancer cells compared to normal conditions, leading to increased cell proliferation, migration and invasion, LNM development and poor prognosis." (PMID 38339387, 2024). "These efforts highlight the potential of targeting NORAD in combination with radiotherapy in promoting a more efficient response to immunotherapy in cancer treatment." (PMID 38339387, 2024). "Studies suggest that NORAD is dysregulated in numerous cancers, including breast, renal, gastric, bladder, pancreatic, ovarian, cervical, prostate, lung and endometrial cancer." (PMID 38339387, 2024). "Quantitative PCR performed for NORAD in three cancer cell lines confirms a higher level of NORAD in Chr20-gain positive cell lines (CACO-2 and HT29)." (PMID 38791575, 2024). "Conversely, NORAD KD has shown inhibitory effects on BC cell viability and migration in vitro and in vivo cancer progression." (PMID 38339387, 2024).
cancer (continued). "Most of the studies describe NORAD as being overexpressed, leading to cancer cell proliferation, invasion and metastatic behavior." (PMID 38339387, 2024). "Currently, research primarily focuses on investigating the expression levels of NORAD in tissue samples to explore its relationship with malignant tumors." (PMID 37993524, 2023). "NORAD has been identified as an oncogene in numerous human cancers, where it was found to be frequently upregulated." (PMID 37993524, 2023). "Tong L, Ao Y, Zhang H, Wang K, Wang Y, Ma Q. Long noncoding RNA NORAD is upregulated in epithelial ovarian cancer and its downregulation suppressed cancer cell functions by competing with miR-155-5p." (PMID 37046403, 2023). "The presence of doxorubicin was shown to significantly decrease the presence of Pumilio 1 proteins independently of NORAD in cancer cells." (PMID 37680988, 2023). "One lncRNA module was confirmed to be associated with cancer metastasis, and nine hub lncRNAs, namely FTX, AC005261.1, NORAD, LINC01578, AC004542.2, ZFAS1, EBLN3P, THUMPD3-AS1, and GAS5, were discovered." (PMID 36514044, 2022). "For instance, NORAD is abundantly expressed in colorectal cancer, osteosarcoma, and prostate cancer and is responsible for cancer cell viability, mobility, invasiveness, and dissemination, as well as unwelcome clinic consequences." (PMID 36245705, 2022). "Overall, NORAD is involved in development of different cancers such as lung cancer, ovarian cancer and osteosarcoma." (PMID 35773731, 2022). "lncRNA NORAD acts as an oncogenic gene to orchestrate cancer progression by regulating cell proliferation and migration." (PMID 34969360, 2022). "As a kind of highly conserved and newly discovered lncRNA, NORAD is dysregulated in various cancers and is deemed as a reliable biomarker for tumor diagnosis and prognostic prediction." (PMID 36245705, 2022). "Analogous to NORAD and GAS5, several other lncRNAs have also been proposed to perturb cancer‐associated cellular pathways through specific interactions with protein binding partners." (PMID 34668345, 2022). "A meta-analysis reported that higher NORAD expression was significantly related with poorer overall survival in cancers." (PMID 35645836, 2022). "Our study elucidated the role of NORAD in cancer cell proliferation, invasion, and migration of LC with the involvement of the miR-28-3p/E2F2 ceRNA network." (PMID 36245705, 2022). "NORAD is another lncRNA, which is reported to be overexpressed in many cancers and several studies have explored its involvement in numerous processes associated with carcinogenesis." (PMID 34202021, 2021). "Several researches have appraised the role of NORAD in the evolution of human cancers with most of them indicating an oncogenic role for this lncRNA." (PMID 34485302, 2021). "Accumulated genomic instability can lead to abnormal metabolism, accelerated aging and cancer development while activating NORAD simultaneously." (PMID 33722248, 2021). "In the current review, we describe the role of NORAD in the evolution of human cancers based on the conducted experiments in cell lines, animal models and human subjects." (PMID 34485302, 2021). "Recent investigations uncovered the essential roles of NORAD in biological processes, which also exerts oncogenic functions among various cancers." (PMID 34551785, 2021). "It has been shown that the interaction of NORAD with Pumilio promotes the molecular decoy of these proteins in cancer cells." (PMID 33739352, 2021). "In this study, analysis of microarray expression profiles between 55 pancreatic ductal adenocarcinoma cells (PDAC) and normal pancreas tissues, showed the significant upregulation of NORAD in cancer patients (p < 0.001)." (PMID 34771549, 2021). "For instance, PVT1 promotes cancer progression in gallbladder cancer; NORAD promotes cell proliferation, invasion, and migration and inhibits apoptosis in lung cancer; and MFI2-AS1 promotes cancer progression and metastasis in hepatocellular carcinoma." (PMID 33737947, 2021).